FGF21 (fibroblast growth factor 21)
Diseases named in the same sentence as FGF21 in open-access papers (continued):
Sharing a sentence is not in itself a finding about the gene and the disease.
Obesity (continued). "Compared to this, FGF21 correlated negatively with the disposition index in the controls with obesity (R = −0.66)." (PMID 37299461, 2023). "Collectively, these findings suggest that Taxifolin exerts its anti-obesity effects through at least two different pathways: directly acting on brown adipocytes and inducing Fgf21 expression in the liver." (PMID 36678220, 2023). "In rodent models with obesity and type 2 diabetes, FGF21 has the effect of reducing blood sugar and lipidemia and can increase energy consumption leading to weight loss." (PMID 36982739, 2023). "Increasing the production of the stress hormone FGF21 prevents diet-induced obesity and NASH in mice fed a high-fat diet." (PMID 36648330, 2023). "A study observed that FGF21 levels were higher in patients with obesity than in patients with normal weight." (PMID 36462120, 2023). "FGF-21 quartiles were positively associated with diabetes indicators (FPG), obesity indicators (BMI, WC, HC, and WHR), hypertension indicators (SBP and DBP) and dyslipidemia indicators (TG) (all P for trend < 0.05)." (PMID 37658393, 2023). "FGF21 analogs have been used in humans and animal models to ameliorate metabolic dyscrasias secondary to obesity." (PMID 36756310, 2023). "The elevated FGF-21 plasma levels in obesity possibly reflect obesity-related FGF21 resistance and the action of endogenous FGF21 inactivation enzymes." (PMID 37189422, 2023). "ATG7 deletion selectively in skeletal muscle inhibits mitophagy and induces FGF21 as a mitokine, leading to protection from obesity and insulin resistance." (PMID 37818094, 2023). "For the superior efficacy of FGF21in handling metabolic diseases, including HP, thus improving FGF21 resistance is a new idea for the treatment of obesity and related metabolic disease." (PMID 37424900, 2023). "In these animals, exercise was shown to induce transcriptional activation of FGFR1 and KLB in adipocytes, resulting in increased sensibility to FGF21, and hence attenuating obesity-induced metabolic dysfunction." (PMID 37019912, 2023). "Here, we summarize recent studies on the relationship between FGF21 and metabolic syndrome (obesity, diabetes, hyperlipidemia, and hypertension), confirming the importance of FGF21 in regulating metabolic syndrome." (PMID 37576954, 2023). "In this pilot study, the acute practice of the novel RVT improved the ISF glucose concentration, FGF21 and myostatin levels, and muscle stiffness and fatigue in middle-aged and older adults with obesity." (PMID 36981616, 2023). "The expression of FGF21 is positively correlated with liver triglycerides and liver fat metabolism—high FGF21 levels are found in obesity, T2DM, and metabolic syndrome." (PMID 38137829, 2023). "Multiple analogues or mimetics of FGF21 have been developed to solve this problem, some of which have completed phase I clinical trials with a noticeable improvement in obesity and T2D‐related symptoms in patients." (PMID 37462619, 2023). "This confirms that FGF-21 secretion is influenced by physiological or environmental stress in people with obesity, as reported in previous studies." (PMID 37436597, 2023). "ob/ob mice treated with RAR agonists showed an anti-obesity phenotype similar to that of mice expressing FGF21 in the liver." (PMID 37576954, 2023). "And the research has identified the promotion of white fat browning by targeting the FGF21–PGC‐1α axis as an attractive treatment for obesity and related metabolic disorders." (PMID 37701204, 2023). "The paradoxical relationship between plasma FGF21 level and obesity was also interpreted as the development of FGF21 resistance in obese subjects." (PMID 36905134, 2023). "Chronic low-grade inflammation is the culprit of metabolically unhealthy obesity, and FGF21 is secreted by the liver upon inflammatory stimuli." (PMID 36761216, 2023).
Obesity (continued). "Apart from ameliorating obesity, elevated serum FGF21 and Irisin levels are beneficial for hypothyroidism, polycystic ovary syndrome, Prader–Willi syndrome, and even can serve in the treatment of severe acute respiratory syndrome coronavirus 2 infection." (PMID 37462619, 2023). "Hepatic phospholipid (PL) saturation, mediated by depletion of a PL remodeling enzyme LPCAT3, protects mice from diet‐induced obesity through FGF21 and elevated energy expenditure." (PMID 37088778, 2023). "On the one hand, FGF21 can increase energy expenditure and attenuate obesity, as shown in obese mice." (PMID 36594101, 2023). "Research on FGF21 in animal and human metabolic diseases such as obesity and diabetes are relatively mature and FGF21 is closely related to diseases or pathological processes such as metabolic syndrome and non-alcoholic fatty liver." (PMID 36968461, 2023). "A case for FGF21 resistance in obesity has been debated, but how that potentially would influence FGF21 responses to nutritional stimuli, or FGF21’s influence on macronutrient preferences, requires future investigation." (PMID 37729024, 2023). "A month after bariatric surgery, patients with obesity exhibited a significant increase in FGF21 levels." (PMID 36462120, 2023). "Loss of SEL1L in myocytes leads to reprogramming of systemic metabolism, including enhanced adipocyte beigeing, increased insulin sensitivity, and resistance to diet-induced obesity, partly through the action of myocyte-derived FGF21." (PMID 37535424, 2023). "Obesity and excess carbohydrate and/or insufficient protein intake were reported to increase FGF21 concentrations." (PMID 37555575, 2023). "In humans, circulating FGF21 levels are elevated in metabolic syndrome, obesity, CVDs, diabetes, non-alcoholic fatty liver disease, mitochondrial myopathies, and cold exposure." (PMID 36028609, 2023). "The depletion of PTEN in hepatocytes of mice significantly induces FGF21, improves muscle insulin sensitivity, and leads to decreased obesity, indicating a certain synergistic effect among the liver, muscle, and fat." (PMID 38069273, 2023). "In the experiments, the researchers used gene therapy to ramp up FGF21 production in the livers of mice that develop obesity and a NASH-like condition when fed a high-fat diet for 23 weeks." (PMID 36648330, 2023). "One study found that FGF21 can efficiently ameliorate obesity-related inflammation in obese mice and 3 T3-L1 preadipocytes, which are mediated by the fibroblast growth factor receptor substrate 2-extracellular regulated protein kinases 1/2 signaling pathway." (PMID 36594101, 2023). "Fibroblast growth factor 21 has been suggested as a promising new drug for treating diabetes and obesity thanks to its multiple metabolic-regulating functions, such as enhancing insulin sensitivity and increasing energy expenditure." (PMID 38116563, 2023). "The myokines represented by FGF21 and Irisin can promote the browning of adipocytes and serve as promising targets for treating obesity." (PMID 37462619, 2023). "As an important endocrine regulator with hormonal effects predominantly expressed in the liver, FGF21 contributes to ketogenesis and ameliorates obesity." (PMID 36615908, 2023). "As for today, several FGF21 analogues and mimetics have progressed to clinical trials in patients with obesity, type 2 diabetes mellitus and NASH." (PMID 37189422, 2023). "Due to these actions, several laboratories have developed FGF21 analogs to treat patients with metabolic disorders such as obesity and diabetes." (PMID 37948566, 2023). "In view of the important role of FGF21 in obesity, the pharmaceutical industry has developed FGF21 analogs or FGF21 receptor agonists to overcome the shortcomings of the natural FGF21 protein, and these treatments have entered the clinical stage." (PMID 37576954, 2023).
Obesity (continued). "However, more and more studies have reported that the elevated human serum FGF21 level was independently associated with HP, obesity, T2DM and fatty liver diseases, which led us to hypothesize that HP in fact may affect the raise of serum FGF21 level, especially in the state of diabetes." (PMID 37424900, 2023). "A recent clinical trial showed that FGF21 analog treatment for 12 weeks significantly improved lipid profiles with increased adiponectin levels in patients with obesity and T2D." (PMID 37755259, 2023). "In people with obesity, acute exercise increases the concentration of FGF-21 in one hour after exercise." (PMID 35250869, 2022). "FGF21 overexpression in the liver via hydrodynamic delivery protects against HFD-induced obesity and adipose inflammation and improves glucose homeostasis." (PMID 35909571, 2022). "On the other hand, FGF21 resistance due to attenuated receptor signaling and consequently impaired induction of target genes in diet-induced obesity (DIO) mice has also been described." (PMID 35909532, 2022). "FGF-21 was found to reduce blood glucose during nutrient sufficiency (for example, obesity or during feeding), whereas it increased blood glucose during nutrient-deficient periods (for example, fasting)." (PMID 36238554, 2022). "Clinical studies have shown that serum FGF-21 levels positively correlated with obesity and fatty liver and that lipid infusion increased FGF-21 levels." (PMID 36362225, 2022). "Our data emphasize the importance of maintaining FGF21 sensitivity in adipose tissue during obesity to resist metabolic complications, as seen in UCP1 KO mice, which remain FGF21-sensitive in iWAT despite increased endogenous FGF21 levels." (PMID 36034414, 2022). "Fibroblast growth factor 21 (FGF21) has emerged as a promising therapeutic agent for the treatment of obesity and T2D." (PMID 36552772, 2022). "FGF21 administration has potent benef icial effects on obesity and diabetes in humans, cynomolgus monkey, and rodents." (PMID 35434487, 2022). "Paradoxically, serum FGF21 levels are elevated in subjects with obesity, metabolic syndrome, NAFLD and coronary artery/heart disease." (PMID 36235821, 2022). "Here, we show that after long-term high fat diet feeding (HFD), circulating FGF21 levels become similarly high in obese wildtype and obesity-resistant UCP1 KO mice, suggesting improved FGF21 sensitivity in UCP1 KO mice." (PMID 36034414, 2022). "Fibroblast growth factor 21 (FGF21) is considered a promising therapeutic agent for obesity and related diseases." (PMID 36034414, 2022). "FGF21 has been proposed as a novel metabolic regulator given its ability to normalize glucose and lipid metabolism and prevent the development of obesity and diabetes." (PMID 36552772, 2022). "In people with obesity, the concentration of FGF-21 increases with physical activity one hour after exercise, which can prevent some diseases, mainly sarcopenia and obesity." (PMID 36362238, 2022). "The mtDNA polymerase POLG mutator mice is also able to induce FGF21 expression, and young POLG mice placed on a HFD are completely resistant to diet-induced obesity." (PMID 39871928, 2022). "FGF-21 activates glucose uptake in adipocytes and is suggested to prevent the development of diabetes mellitus and obesity by its ability to normalize glucose and lipid homeostasis." (PMID 35147910, 2022). "Peripheral 5-HT upregulates hepatic FGF21 expression and plasma FGF21 levels, leading to metabolic diseases such as obesity, insulin resistance, type 2 diabetes, and NAFLD." (PMID 35163521, 2022). "Although some animal studies have suggested the therapeutic potential of FGF-19 and FGF-21 in the treatment of obesity, diabetes or metabolic syndrome, still little is known about their role in the metabolic disorders." (PMID 36362225, 2022).
Obesity (continued). "The protective effects of CO exposures against ER stress- or diet-induced, obesity-dependent hepatic steatosis were found to be dependent on increased fibroblast growth factor 21 (FGF21) expression in hepatocytes and liver." (PMID 35326205, 2022). "FGF21 levels are positively correlated with obesity, body mass index (BMI) and hepatic fat accumulation." (PMID 36457562, 2022). "FGF21: Fibroblast growth factor 21 (FGF21) is a myokine with multiple therapeutic benefits against obesity-related medical complications." (PMID 35563026, 2022). "Endogenous FGF21 serum levels, however, are increased during obesity-related diseases, suggesting the development of FGF21 resistance during obesity and thereby lowering FGF21 efficacy." (PMID 36034414, 2022). "Progress to improve, for example, the pharmacokinetic properties (e.g., bioavailability and delivery) of these FGF21-mimicking compounds are now required to improve the efficacy of these therapies against human obesity, IR and T2D." (PMID 35409319, 2022). "In our study, we used a model of diet-induced obesity and non-alcoholic fatty liver disease to study the effect of subcutaneously administered FGF21 on long-term fertility." (PMID 36406708, 2022). "As a novel metabolic regulator, FGF21 plays a critical role in promoting glucose uptake and lipid metabolism in obesity." (PMID 35909571, 2022). "Numerous subsequent studies confirmed the increase of endogenously circulating FGF21 levels during obesity and metabolic disease in mice and humans." (PMID 36034414, 2022). "Conversely, the pro-inflammatory cytokine TNF-α downregulates the levels of β-Klotho and induces inflammation, thus impairing the beneficial effects of FGF21 on obesity and ER stress." (PMID 35909571, 2022). "Regarding the pathogenesis of physical exercise, studies using rodent models have shown that exercise alleviates obesity-induced metabolic disorders by affecting the expression of fibroblast growth factor 21 (FGF21)." (PMID 36340766, 2022). "FGF21, released by myocytes upon exposure to cold or exercise, protects the body against obesity and insulin resistance, in part by antagonizing adipokines released by adipose tissue." (PMID 35011721, 2022). "FGF-21 has multiple appreciated roles in physiology including potent effects on obesity, clearance of systemic glucose and lipids, improvement of insulin sensitivity and inhibition of oxidative stress." (PMID 35013379, 2022). "FGF21 stimulates glucose uptake in adipocytes, and FGF21 transgenic mice became resistant to diet-induced obesity." (PMID 35012677, 2022). "Serum FGF21 level significantly increases after 2 weeks of exercise, but drops after 36 weeks of exercise in patients with obesity and after 12 weeks in obese rats." (PMID 36006939, 2022). "Our results here confirm that targeting Mat1a protects the liver from the obesity-induced hepatosteatosis through the formation of FGF21." (PMID 35232994, 2022). "The FGF21 analogue LY2405319 was subcutaneously administered for 28 days to patients with obesity and T2DM, resulting in attenuated dyslipidaemia, reduced body weight and plasma insulin, and increased adiponectin levels." (PMID 36362103, 2022). "The expression of FGF21 in WAT is also increased during obesity when adipose PPARγ is activated to promote adipogenesis and lipid accumulation." (PMID 35159314, 2022). "Recent studies have shown that the administration of an FGF21 analog to humans with obesity significantly lowered body weight and decreased LDL cholesterol and triglycerides while increasing HDL cholesterol." (PMID 36012166, 2022). "The administration of exogenous FGF21 in mice and primates improves obesity-related insulin resistance, glucose and lipid homeostasis, further suggesting a major role in the regulation of systemic metabolism." (PMID 36034414, 2022). "FGF21 levels are increased in patients with obesity, which suggests that obesity is a state of FGF21 resistance." (PMID 35328759, 2022).
Obesity (continued). "In this context of obesity, with high increased serum FGF21 levels, dietary lipids, fatty acids released by lipolysis of the WAT and those secreted by the liver into VLDL were mainly moved towards the BAT to be catabolized through FAO." (PMID 35232994, 2022). "Studies have shown that the serum FGF21 level in individuals or animals with obesity decreases after aerobic exercise, consistent with the findings of our study." (PMID 36006939, 2022). "Serum biomarker analyses have revealed elevated FGF21 levels in patients with metabolic disease related to obesity and insulin resistance." (PMID 35663311, 2022). "Paradoxically despite its beneficial action, FGF21 is elevated in insulin resistance states i.e. fatty liver, obesity, and type 2 diabetes." (PMID 35909532, 2022). "Contrary to the metabolic improvements by FGF21 administration, endogenous FGF21 serum levels are increased during obesity-related diseases, suggesting FGF21 resistance." (PMID 36034414, 2022). "It was concluded that obesity represents a state of resistance to FGF21, as increased serum levels of FGF21 have been reported in experimental animals (mice) and in humans." (PMID 35054828, 2022). "The changes in lipid profiles, hormones and lipoproteins indicate a metabolically healthy obesity (MHO) phenotype, which is most likely caused by strong hepatic upregulation of the hepatokine fibroblast growth factor 21 (FGF21)." (PMID 35626717, 2022). "Plasma FGF21 levels correlate with the severity of non-alcoholic steatohepatitis in subjects with obesity and type 2 diabetes." (PMID 35163521, 2022). "Since obesity or metabolic stress can affect diverse aspects of autophagy or lysosomal function and cancer tissue could be deficient in autophagy, FGF21 produced by autophagy-deficient hepatocytes due to genetic or metabolic causes may affect the behavior of hepatoma with autophagy insufficiency." (PMID 35321438, 2022). "Another proposed explanation is that obesity leads to FGF-21 resistance and that FGF-21 levels are increased in obese subjects as a compensatory mechanism." (PMID 35147910, 2022). "FGF21 is strongly influenced, among others, by TNFα, which is known to be upregulated in obesity-induced inflammation." (PMID 36034917, 2022). "It is known that peptide 20 potently reversed metabolic disorders in rodent models of obesity and diabetes, characteristic of increased energy expenditure and elevated circulating FGF21 levels as a result of GCGR agonism." (PMID 35217653, 2022). "In conclusion, our findings are coherent with recent research by supporting the concept of requiring sustained FGF21-sensitivity in adipose tissue for metabolic improvements during obesity and insulin resistance." (PMID 36034414, 2022). "Butyrate activates FGF21 in vitro, and FGF21 overexpression in transgenic mice has shown to prevent diet‐induced obesity." (PMID 35856338, 2022). "Nevertheless, these findings indicate that obesity-induced downregulation of the receptor complexes can reduce tissue specific FGF21 responsiveness/sensitivity." (PMID 36034414, 2022). "NAMPT induces FGF21 and reverses metabolic derangements in diet-induced and genetic models of obesity and glucose intolerance." (PMID 35228549, 2022). "Although FGF21 has several beneficial effects for glucose and lipid metabolism, circulating FGF21 levels are paradoxically increased in humans with obesity, metabolic syndrome, and NAFLD." (PMID 35163521, 2022). "Serum levels of FGF21 are increased in individuals with obesity, type 2 diabetes, and metabolic syndromes." (PMID 36035417, 2022). "Consistent with its function, some studies have found that the anti-obesity effects and glucose-lowering effects of metformin are also exerted by FGF21." (PMID 36484892, 2022). "In our previous publication, we performed next generation RNA sequencing in several peripheral tissues to gain molecular insights on how FGF21 controls the obesity resistance in UCP1 KO mice." (PMID 36034414, 2022).